MALAT1 (metastasis associated lung adenocarcinoma transcript 1)
Diseases named in the same sentence as MALAT1 in open-access papers (continued):
Sharing a sentence is not in itself a finding about the gene and the disease.
breast cancer (continued). "In human breast cancer tissues, MALAT1 has been reported to be aberrantly up-regulated and high levels of MALAT1 expression correlate with poor patient prognosis." (PMID 32174966, 2020). "In their study comprised of 80 patients with breast cancer and 80 controls, MALAT1 expression was shown to be positively correlated with lymph node, ER status, tumor stage, and histological grade, indicating its possible prognostic value." (PMID 32708561, 2020). "Conversely, MALAT1 overexpression inhibited breast cancer metastasis in transgenic, xenograft, and syngeneic models." (PMID 32929060, 2020). "Malat1 was also demonstrated to be induced in kidneys of hypoxic mice, and Malat1 was identified as one of the most upregulated non-coding transcripts upon hypoxia in a breast cancer cell line." (PMID 32503170, 2020). "By binding to the transcription factor TEAD, MALAT1 suppresses metastasis gene expression, colorectal and breast cancer cell migration, invasion, and metastasis in vitro and in mice." (PMID 32174966, 2020). "Kaplan-Meier (KM) survival analysis shows that a lower level of MALAT1 in breast cancer tissues correlates with shorter distant metastasis-free survival." (PMID 32174966, 2020). "For instance, MALAT1 downregulation was achieved through use of CRISPR/Cas9 to study the MALAT1 effects on breast cancer metastatic incidence." (PMID 32929060, 2020). "Inhibition of PI3K/Akt pathway by its inhibitors, MK-2066, and GDC0941, revealed the upregulation of FOXO1 and downregulation of MALAT1 in breast cancer cells." (PMID 32708561, 2020). "MALAT-1 has also been shown to induce epithelial–mesenchymal transition through the miR-204/ZEB2 axis in breast cancer." (PMID 32700729, 2020). "In breast cancer cells that were resistant to trastuzumab and/or tamoxifen, MALAT1 was one of the most significantly upregulated molecules, compared to cancer cells that were sensitive to treatment." (PMID 32708561, 2020). "Within breast cancer cell lines, the highest expression of MALAT1 was seen in metastatic TNBC cells, MB231 and trastuzumab-resistant HER2+ cells, JIMT1." (PMID 32708561, 2020). "Further, the MALAT1 locus was shown to exhibit tandem duplication in some breast cancers resulting in increased dosage of the gene." (PMID 32503170, 2020). "For example, MALAT1 acts as a ceRNA for some miRNAs, such as miR-124, miR-1, miR-129-5p, miR-204, and miR-339-5p, thus promoting breast cancer progression." (PMID 32486413, 2020). "The roles of MALAT1 in breast cancer are complicated, because both oncogenic and tumor-suppressive roles of MALAT1 in breast cancer have been reported." (PMID 32486413, 2020). "MALAT1 was reported to suppress breast cancer metastasis in the transgenic, xenograft, and syngeneic models." (PMID 33178684, 2020). "We found in this study that FOXO1 plays a regulatory role in mediating MALAT1 expression in breast cancer cells via the PI3/Akt pathway." (PMID 32708561, 2020). "The results from our study bolster the findings from most studies and concur with an oncogenic role of MALAT1 in breast cancer." (PMID 32708561, 2020). "We designed this study to examine the role of MALAT1 in breast cancer and its association with HER2+ breast cancer cells resistant to trastuzumab." (PMID 32708561, 2020). "RUNX1 was recently shown to regulate lncRNAs NEAT1 and MALAT1, which have critical roles in the onset and progression of breast cancer." (PMID 32655837, 2020). "In vivo assay using transgenic, xenograft and syngeneic models consistently showed a metastasis‐inhibitory role of MALAT1 in breast cancer." (PMID 32779318, 2020). "It is therefore likely that MALAT1 suppresses colorectal and breast cancer cell migration, invasion, and metastasis." (PMID 32174966, 2020). "Collectively, the results indicated that increased MALAT-1 expression in breast cancer was related to a worse OS (HR = 2.06, 95% CI: 1.66–2.56, P<0.0001)." (PMID 32700729, 2020).
breast cancer (continued). "Our study examined the role of MALAT1 in breast cancer and the mechanisms involved in the regulation of MALAT1." (PMID 32708561, 2020). "In keeping with this, MALAT1 knockdown has been proposed as a promising strategy to block the metastatic capacity of breast cancer." (PMID 33142861, 2020). "In contrast, MALAT1 functions as a ceRNA for miR-20a to inhibit the growth and metastasis of breast cancer." (PMID 32486413, 2020). "lncRNA MALAT1 was identified as a metastasis-suppressing lncRNA in breast cancer that was inversely correlated with breast cancer progression and metastatic ability." (PMID 32368305, 2020). "Taken together, the extensive range of functions of MALAT-1 enables it to predict survival outcomes in patients with breast cancer." (PMID 32700729, 2020). "For example, MALAT1, which has previously been described as a metastasis-promoting lncRNA, has recently been found to suppress breast cancer metastasis." (PMID 32742478, 2020). "Pooled HR demonstrated that elevated MALAT-1 expression significantly predicted unfavorable overall survival (HR = 2.06, 95% CI: 1.66–2.56, P<0.0001) in patients with breast cancer." (PMID 32700729, 2020). "In a French study using real-time PCR and reverse phase protein array (RPPA) techniques, MALAT1 was overexpressed in mammary tumors." (PMID 32872162, 2020). "Here, we pooled published data to highlight the prognostic and clinical value of MALAT-1 in breast cancer." (PMID 32700729, 2020). "Despite accumulating evidence that MALAT1 plays a pro-oncogenic and pro-metastatic role in a wide range of cancers, including mammary cancer a few recent studies reported a tumor suppressor-like role for Malat1." (PMID 32503170, 2020). "Elevated MALAT-1 expression levels in breast cancer were reported in most studies, except in one study that reported the down-regulation of MALAT-1." (PMID 32700729, 2020). "Further investigation is warranted using more biomarkers associated with tumor metastasis and designing a cohort study with a larger sample size of breast cancer patients to assess the role of MALAT1 in breast cancer invasion, metastasis, and disease outcome." (PMID 32708561, 2020). "For instance, breast cancer progression can be inhibited by systemic knockdown of MALAT1 using ASO53,140,141." (PMID 32929060, 2020). "These different observations on the role of MALAT1 in breast cancer warrant additional studies to explore the functional role of MALAT1." (PMID 32708561, 2020). "Patients with breast cancer having elevated MALAT-1 expression levels displayed worse survival outcomes (both OS and DFS/RFS/DSS)." (PMID 32700729, 2020). "We evaluated the expression of MALAT1 in seven breast cancer cell lines that included ER+/HER2-, ER+/HER2+, ER-/HER2+, and TNBC cell lines." (PMID 32708561, 2020). "Expression of MALAT1 in breast cancers has the potential to predict the response to cancer treatment and cancer prognosis." (PMID 32708561, 2020). "By forming a RNA-protein complex with TEAD and down-regulating EpCAM, ITGB4 and VEGF expression, MALAT1 suppresses colorectal and breast cancer cell migration, invasion, and metastasis." (PMID 32174966, 2020). "MALAT1 was obviously downregulated in breast cancer than parental tissue, and its level was negatively correlated with cancer progression and metastasis potential." (PMID 32779318, 2020). "Upregulation of MALAT1 in breast cancer induces EMT and decreases trastuzumab sensitivity in HER2+ breast cancer, and the mechanism is associated with PI3/Akt-mediated FOXO1 nuclear retention." (PMID 32708561, 2020).
breast cancer (continued). "Conversely, overexpression of MALAT1 suppressed breast cancer lung metastasis in transgenic, xenograft, and syngeneic models." (PMID 32503290, 2020). "In this specific report, downregulation of MALAT1 was found to increase lung metastases of breast cancer cells." (PMID 32728178, 2020). "Both Malat1 and TDP-43 have been implicated in the pathology of many different cancers, particularly breast cancer." (PMID 31863590, 2020). "In agreement with previous reports, our analysis also showed that NEAT1 and MALAT1 were enriched in ER+ breast cancers." (PMID 32244924, 2020). "Of the different subtypes of breast cancer cell lines, the highest level of MALAT1 was seen in metastatic TNBC and trastuzumab-resistant HER2+ cells." (PMID 32708561, 2020). "Knockdown of MALAT1 using antisense oligonucleotides (ASOs) in the mouse mammary tumor virus (MMTV)-PyMT mouse mammary carcinoma model results in slower tumor growth accompanied by significant differentiation into cystic tumors and a reduction in metastasis." (PMID 32708561, 2020). "The expression of MALAT1 was measured in seven pairs of breast cancer tissues and adjacent normal tissues." (PMID 30683807, 2019). "Here, we demonstrate that TALAM1 synergizes with MALAT1 during tumorigenesis in aggressive breast cancer." (PMID 31382922, 2019). "It was reported that MALAT1 is increased in breast cancer tissues and is involved in several cellular processes, including transcriptional and post-transcriptional regulation." (PMID 30982780, 2019). "In the present study, the expression of MALAT1 in clinical samples of breast cancer tissues was found to be significantly up-regulated that was consistent with the result based on the dataset of the Cancer Genome Atlas (TCGA) at cBioportal." (PMID 30683807, 2019). "For instance, down-regulation of MALAT1 promoted migration and invasion in breast cancer cells and induced EMT by regulating the PI3K–AKT pathway." (PMID 30683807, 2019). "To further characterize the presence and biological function of TALAM1 we decided to use human representative breast cancer cell lines with different biological and aggressiveness properties, a model known to be regulated by MALAT1." (PMID 31382922, 2019). "Since MALAT1 is highly expressed in metastases of human breast cancer, the authors suggested further clinical investigation to evaluate this therapy to support breast cancer treatment." (PMID 31003545, 2019). "The present study aims to explore the expression level of MALAT1 in breast cancer samples by qRT-PCR and to analyze the clinical significance of MALAT1 using the data from TCGA at cBioportal." (PMID 30683807, 2019). "In summary, we demonstrate for the first time that PNPO and MALAT1 are up-regulated, while miR-216b-5p is down-regulated, in human breast cancer." (PMID 30982780, 2019). "Previously, it has been reported that MALAT1 knockdown in breast cancer resulted in alterations in gene expression signatures correlating with differentiation and pro-metastatic signalling." (PMID 31382922, 2019). "To investigate the miRNA-related functions of MALAT1 in breast cancer, we chose miR-339-5p as a model miRNA for further studies, with a particular focus on the target gene BLCAP." (PMID 30683807, 2019). "The study found MALAT1 to be more sensitive than CA15-3 which is the current marker for breast cancer." (PMID 31404988, 2019). "MALAT1 expression has been linked to EMT promotion in several cell types and its role on the process seemed contradictory, especially in breast cancer cells." (PMID 31003545, 2019). "Further, the suppression of the lncRNA Malat1 using an ASO resulted in up to an 80% inhibition of metastasis in a luminal B breast cancer mouse model." (PMID 31623640, 2019). "Here, the expression of MALAT1 in breast cancer samples was examined and the TCGA database at cBioportal was used to verify the results." (PMID 30683807, 2019).
breast cancer (continued). "Here we show that TALAM1 synergizes with MALAT1 on the regulation of the migratory capacity of human breast cancer cells." (PMID 31382922, 2019). "Recently, our group performed a chromatin isolation by RNA purification coupled to mass spectrometry (ChIRP-MS) assay to identify Malat1’s endogenous binding proteins in mammary tumors from MMTV-PyMT mice." (PMID 30781877, 2019). "The plasma level of MALAT1 is increased in patients with early fever after breast cancer surgery, but the inflammatory responses and metastasis of lung are decreased significantly after down-regulation of MALAT1." (PMID 31304004, 2019). "Dysregulated expression of MALAT1 has been found in breast cancer and is involved in a variety of signaling pathways, which makes it a star molecule with multiple functions." (PMID 30982780, 2019). "Taken together, targeted inactivation, restoration (genetic rescue), and overexpression of MALAT1 in multiple in vivo models suggest that the lncRNA MALAT1 suppresses breast cancer metastasis." (PMID 30781877, 2019). "On the other hand, several studies showed that the expression of MALAT1 is downregulated in glioma, colorectal cancer, and breast cancer." (PMID 30781877, 2019). "The results demonstrated that MALAT1 was up-regulated in breast cancer tissues, which was in agreement with previous reports about up-regulation of MALAT1 in non-small cell lung cancer (NSCLC) and hepatocellular carcinoma." (PMID 30683807, 2019). "Genetic rescue experiments unambiguously established a novel tumor suppressor role for MALAT1 by toppling the decade-old claim of MALAT1 being an oncogene in breast cancer." (PMID 31141943, 2019). "The expression of MALAT1 in triple negative and Her-2 positive breast cancers was positively correlated to the number of metastatic lymph nodes in patients with breast cancer." (PMID 29416769, 2018). "Our initial screens of breast cancer MDA-MB-231 cells showed that Malat1 expression was positively correlated with the level of Nischarin present in the cell." (PMID 29912916, 2018). "With varying expressions in different molecular subtypes of breast cancer, MALAT1 has distinct mechanisms of action." (PMID 29416769, 2018). "Data from the Curtis Breast Statistics database similarly indicate that Malat1 tends to be reduced in breast cancer tissues versus control." (PMID 29912916, 2018). "Deletion of MALAT1 or treatment with antisense oligonucleotides targeting MALAT1 has been shown to promote differentiation of mammary tumors and prevent metastasis in experimental mice." (PMID 29520069, 2018). "On the other hand, the expressions of MALAT1 increased under anaerobic conditions, which suggested that MALAT1 would play crucial roles in development and metastasis of breast cancer." (PMID 29416769, 2018). "In this study, the expressions of MALAT1 in samples with triple negative and Her-2 positive breast cancer, which are two kinds of breast cancer with the highest degree of malignancy and the poorest prognosis, were detected." (PMID 29416769, 2018). "In the present study, we investigate the role of Malat1 and the effects of Malat1 KO in a breast cancer cell model." (PMID 29912916, 2018). "MALAT1 promotes proliferation and invasion abilities of breast cancer cells through XBP1 (X-box binding protein 1)-HIF (hypoxia-inducible factor)-1α pathway in MDA-MB-231 and through Her-2 pathway in MDA-MD-435." (PMID 29416769, 2018). "The downregulation of MALAT1 induces EMT via the PI3K/Akt pathway in breast cancer, and in contrast, the upregulation of MALAT1 promotes the metastasis of osteosarcoma cells by activating the PI3K/Akt pathway." (PMID 29416704, 2018). "The alterations of expressions of MALAT1 and related genes were detected by qRT-PCR in two breast cancer cell lines." (PMID 29416769, 2018). "In breast cancer, Malat1 has alternatively been described as either a tumor suppressor or an oncogene." (PMID 29912916, 2018).
breast cancer (continued). "We and others have demonstrated the involvement of MALAT1 in breast cancer progression and metastasis." (PMID 30496290, 2018). "MALAT-1 has been demonstrated to be up-regulated in many types of cancer, such as prostate cancer, breast cancer and monocytic leukemia." (PMID 30285605, 2018). "In the present study, we investigate the role of Malat1 in breast cancer in the expression background of the gene Nischarin, a protein previously characterized by our lab." (PMID 29912916, 2018). "In both types of breast cancer, different signaling pathways promote tumorgenesis and progression through a common effector molecule, which is known as MALAT1." (PMID 29416769, 2018). "Our study suggested that MALAT1 is a core signaling molecule for promoting development and migration of triple negative and Her-2 positive breast cancers." (PMID 29416769, 2018). "Serum levels of MALAT1, as examined by quantitative real-time PCR (qPCR), were higher in breast cancer patients (n = 157) than normal women (n = 107)." (PMID 30545127, 2018). "Among individual transcripts identified by this analysis were several genes known to be associated with the metastatic process (ALCAM, MALAT1) and EMT (SNAI1, GSC, FOXC2, SIP1) and breast cancer stem cells (CD44)." (PMID 29291741, 2018). "Reassuringly, invasive breast cancer tissues have a higher MALAT1 staining and the mean area intensity is higher in both invasive tissues as compared to NAT." (PMID 30189670, 2018). "In breast cancer, MALAT1 regulates critical processes such as tumor growth, differentiation, and metastasis." (PMID 28793797, 2018). "Altogether, we suggested that MALAT1 would become a common biomarker for prognosis of triple negative and Her-2 positive breast cancer." (PMID 29416769, 2018). "Among samples with Her-2 positive breast cancer, the expressions of MALAT1 were significantly higher in highly metastatic samples compared with non-metastatic samples." (PMID 29416769, 2018). "Nevertheless, there are few studies about the mechanisms by which MALAT1 is involved in the progression of breast cancer, especially breast cancer with different molecular subtypes." (PMID 29416769, 2018). "MALAT1 is a highly conserved lncRNA that is highly expressed in several types of cancer, including breast cancer." (PMID 29416769, 2018). "The expressions of MALAT1 were significantly higher in samples with TNBC than those in samples with Her-2 positive breast cancer." (PMID 29416769, 2018). "Since both Nisch and Malat1 appear to confer an inhibitory effect upon cell growth and migration in breast cancer, we expected these genes to be reduced in breast tumors compared to normal tissue controls." (PMID 29912916, 2018). "According to the research findings in this study, MALAT1 shows much higher expressions in samples with TNBC than samples with Her-2 positive breast cancer." (PMID 29416769, 2018). "The results showed that lncRNAs AFAPA-AS1, aHIF, BDNF-AS, HYMAI, UCA1, kucg 1, MALAT1 were differentially expressed in breast cancer tissues (fold change > 2)." (PMID 28938549, 2017). "For instance, downregulation of MALAT-1 inhibits PI3K/Akt signalling in osteosarcoma cells, whilst in contrast, in breast cancer cells, MALAT-1 knockdown was found to lead to increased PI3K/Akt signalling and EMT induction." (PMID 28430163, 2017). "It was identified that MALAT1 is highly expressed in hepatocellular cancer, breast cancer, and colorectal cancer." (PMID 28039476, 2017). "Later, accumulated evidence has shown that MALAT1 is elevated in a broad spectrum of cancer types, including breast cancer." (PMID 27732939, 2017). "MALAT1 induced migration and invasion of human breast cancer cells by competitively binding miR-1 with cdc42." (PMID 28396617, 2017). "Other EMT associated lncRNAs which have been shown to affect tamoxifen sensitivity in breast cancer include MALAT-1, lncRNA-ROR, and HOTAIR." (PMID 28430163, 2017).